NLRP3 (NLR family pyrin domain containing 3)
Diseases named in the same sentence as NLRP3 in open-access papers (continued):
Sharing a sentence is not in itself a finding about the gene and the disease.
Myalgia (4 papers, 2016 to 2023). "It is interesting to note that NLRP3 genetic variants (namely, NLPR3 rs10157379 T > C and NLPR3 rs10754558 C > G variants) are associated with fatigue, myalgia, hyperalgesia, and malaise in the acute infectious phase." (PMID 36675440, 2023). "CAPS is caused by gain-of-function mutations in the NLRP3 gene, which encodes cryopyrin, resulting in increased IL-1 secretion; clinical manifestations of CAPS include cold-induced episodes, urticaria-like rash, sensorineural hearing loss, chronic meningitis, myalgia and arthritis." (PMID 35958618, 2022).
myeloid malignancies (4 papers, 2021 to 2024). "MCC950, a selective NLRP3 inhibitor, could be a promising drug candidate to stop the advancement of myeloid malignancies caused by NLRP3-mediated illness." (PMID 36902299, 2023). "Regarding hematological malignancies, the role of NLRP3 inflammasome aberrations originally gained interest in the field of myeloid neoplasms." (PMID 38397043, 2024). "Further, MCC950 is a specific NLRP3 inhibitor and represents a promising molecule to target NLRP3 mediated disease progression in myeloid malignancies." (PMID 35155452, 2021).
myopia (4 papers, 2023 to 2025). "LPIN2 mutations link to increased IL-1β and activated NLRP3 inflammasome and may be related to myopia." (PMID 37965330, 2023). "Considering the role of NLRP3 activation and inflammation in the progression of myopia, it is reasonable to hypothesize that MCC950 could potentially reduce the inflammatory response associated with myopia by inhibiting the expression of NLRP3, thereby slowing down disease progression." (PMID 37958819, 2023). "In the mouse model of simple myopia, scleral NLRP3 inflammasome activation is linked with MMP-2 upregulation, scleral matrix remodeling, and myopia progression." (PMID 40909333, 2025). "In our previous study, we demonstrated the involvement of NLRP3 signaling pathway-related cytokines in the progression of myopia in FDM modeling using both wild-type mice and NLRP3−/− mice." (PMID 37958819, 2023). "In our previous study, we confirmed that changes in the expression levels of NLRP3 in the FDM mouse model do indeed affect the progression of myopia." (PMID 37958819, 2023). "In conclusion, the intraperitoneal injection of MCC950 can attenuate the progression of myopia in FDM by downregulating the expression levels of NLRP3 and its downstream signaling pathway factors (IL-1β, IL-18, Caspase-1, and MMP-2)." (PMID 37958819, 2023). "In this study, we investigated its inhibitory effect on myopia progression by regulating the NLRP3 pathway in the sclera." (PMID 37958819, 2023). "Considering the lack of effective drugs for treating myopia and the growing number of myopia patients, this study aims to offer preliminary experimental evidence for utilizing NLRP3 inhibitors to regulate myopia progression." (PMID 37958819, 2023). "After confirming the effect of MCC950 on the refractive, axial and myopia-related factor in FDM mice, we proceeded to investigate its impact on the expression of factors associated with the NLRP3 signaling pathway." (PMID 37958819, 2023). "This study aimed to investigate the effect of MCC950, an inhibitor of NLRP3, on the progression of myopia using a mouse form-deprivation myopia (FDM) model." (PMID 37958819, 2023). "In the present study, we aimed to further explore whether the NLRP3 inhibitor MCC950 could attenuate the progression of myopia in mice." (PMID 37958819, 2023). "The intraperitoneal injection of MCC950 can inhibit the progression of myopia in FDM mice, possibly by regulating collagen remodeling in the sclera through the NLRP3-MMP-2 signaling pathway." (PMID 37958819, 2023).
nephrotic syndrome (4 papers, 2022 to 2024). A collection of symptoms that include severe edema, proteinuria, and hypoalbuminemia; it is indicative of renal dysfunction. "In this study, methylation of the NLRP3 gene promotor, which should result in decreased NLRP3 gene expression, was significantly higher in PBMCs from patients with glucocorticoid-sensitive nephrotic syndrome." (PMID 35204131, 2022). "In peripheral blood mononuclear cells (PBMCs) from patients with glucocorticoid-resistant nephrotic syndrome, NLRP3 protein co-localized with ASC protein, which could indicate inflammasome activation." (PMID 35204131, 2022). "Its inhibition by CHOP deletion suppresses NLRP3 inflammasome activation and p-ASK1-dependent mitochondrial apoptosis, which decreased albuminuria and improved renal function in nephrotic syndrome (NS)." (PMID 38791453, 2024). "The expression of NLRP3, Casapase-1, GSDMD, IL-1β, and α-SMA in the renal tissue of nephrotic syndrome rats increased, E-cadherin decreased, and Tunel staining showed that an increase of renal tubular epithelial cells with broken nuclei." (PMID 38995910, 2024).
nonalcoholic fatty liver (4 papers, 2017 to 2023). "Moreover, the nonalcoholic fatty liver mouse models require NLRP3 inflammasome activation for hepatitis inflammation and fibrosis." (PMID 36834849, 2023). "Recently, one study reported that naringenin, a flavonoid compound, could downregulate NLRP3 to attenuate nonalcoholic fatty liver in mice." (PMID 35073994, 2022).
Opportunistic infection (4 papers, 2021 to 2025). An infection that is caused by a pathogen that would generally not be able to cause an infection in a host with a normal immune system. "Due to their specificity, drugs directly inhibiting NLRP3 reduce the risk of opportunistic infection and tend to have better safety profiles." (PMID 39816134, 2025). "This is of particular relevance when considering that in a targeted anti-NLRP3 therapy, other pathogen-recognizing inflammasomes can be engaged to produce IL-1β, thus reducing the risk of immune suppression and opportunistic infections." (PMID 34513923, 2021). "Increased specificity afforded by directly blocking NLRP3 would not prevent activation of the other members of the NOD family, therefore, the risk of opportunist infection reported with anti-IL-1 biologics should be more limited with NLRP3 inhibitors." (PMID 39188718, 2024).
oral diseases (4 papers, 2022 to 2026). "The NLRP3 inflammasome was found to be involved in the development of gingival inflammation and alveolar bone loss, suggesting that NLRP3 plays a role in oral diseases." (PMID 35052653, 2022). "This review summarizes current and past evidence on the role of the NLRP3 inflammasome in oral disease development, highlights emerging pharmacological strategies, and outlines future research directions." (PMID 41596738, 2026). "Although research on the role of NLRP3 in oral diseases is expanding, the available data remain fragmented, and comprehensive reviews on this topic are scarce." (PMID 41596738, 2026). "Further investigations of the exact mechanism and functional verification are needed to clarify the synergistic effect of smoking and Candida and the exact role of the NLRP3 inflammasome in the pathogenesis of oral disorders." (PMID 37723958, 2024). "In oral diseases, multiple cellular stressors can act as DAMPs that promote NLRP3 activation." (PMID 41596738, 2026). "Therefore, this review integrates current understanding of NLRP3 inflammasome activation in oral diseases, its impact on disease progression, and emerging therapeutic prospects." (PMID 41596738, 2026). "Several studies have also indicated that the NLRP3 inflammasome plays a key role in the pathogenesis of several common oral diseases, including periodontitis, dental pulp disease, oral lichen planus, and oral cancer, by mediating inflammatory and adaptive immune responses." (PMID 37723958, 2024). "Our results suggested that in oral epithelial cells, NLRP3 inflammasome might be one of the target pathways through which CSE attenuates innate immunity and leads to oral disorders, including oral leukoplakia." (PMID 37723958, 2024). "Our results suggested that in oral epithelial cells, the NLRP3 inflam-masome might be one of the target pathways by which CSE attenuates innate immunity and leads to oral disorders." (PMID 37723958, 2024).
Oral ulcer (4 papers, 2016 to 2022). Erosion of the mucous mebrane of the mouth with local excavation of the surface, resulting from the sloughing of inflammatory necrotic tissue. "Oral ulcers were improved; however, following addition of the PDE4 inhibitor, apremilast, to her treatment regimen, suggesting that signalling pathways other than those directly mediated by the NLRP3 inflammasome were dysregulated." (PMID 34671876, 2022). "Of the two families already described, one reported no further NLRP3-AID symptoms, whereas members of the second family reported autoinflammatory signs and symptoms including oral ulcers but without serologic signs of inflammation." (PMID 34671876, 2022).
paracoccidioidomycosis (4 papers, 2015 to 2021). A systemic fungal infection caused by Paracoccidioides brasiliensis that is most often seen in immunocompromised patients. "However, the role of NLRP3 inflammasome was scantily investigated in pulmonary paracoccidioidomycosis (PCM), leading us to use an intratracheal (i.t.)model of infection to study the influence of this receptor in anti-fungal immunity and severity of infection." (PMID 28740491, 2017). "Higher intracellular protein expression of NLRP3, CASP-1, ASC, and IL-1β and increased priming in mRNA levels of NLRP3 inflammasome genes in monocytes isolated from patients with a chronic form of paracoccidioidomycosis was also reported in comparison to controls." (PMID 33668671, 2021).
paroxysmal AF (4 papers, 2023 to 2024). "The expression of leukocyte GPR43 mRNA in patients with paroxysmal AF (pAF) and persistent AF (psAF) represented a decreasing trend, while NLRP3 was gradually increased." (PMID 38622672, 2024). "In addition, NLRP3 inflammasome activity is increased in atrial cardiomyocytes of patients with paroxysmal AF or long-lasting persistent AF." (PMID 38783894, 2024).
pericardial effusion (4 papers, 2022 to 2025). Fluid collection within the pericardial sac, usually due to inflammation. "In following experiments of recovery, blocking NLRP3 inflammasome with nonsteroidal anti-inflammatory drugs, colchicine, and NLRP3 inhibitor 16673-34-0 all showed a reduction in pericardial effusion or pericardial thickness." (PMID 36204568, 2022).
PFAPA syndrome (4 papers, 2015 to 2024). An auto inflammatory syndrome characterized by recurrent febrile episodes associated with aphthous stomatitis, pharyngitis and cervical adenitis. "The NLRP3 Q703K variant is associated with various autoinflammatory diseases (PFAPA syndrome, CAPS and undefined AID)." (PMID 32477355, 2020). "Recent study on predominant mutations in MEFV, CARD15/NOD2, TNFr1A, and NLRP3 genes in patients diagnosed with PFAPA syndrome showed that 19 of 57 patients carried one or more of the variants tested, with MEFV gene variants being found in 16 patients." (PMID 25821352, 2015). "DNA of patients with PFAPA syndrome was analyzed for the 3 genes associated with monogenic periodic fever (NLRP3, MEFV, and MVK) and for the AIM2 gene." (PMID 25821352, 2015). "A previous study demonstrated a higher frequency of CARD8-FS, whose product loses CARD8 activity and activates the NLRP3 inflammasome, in patients with the PFAPA syndrome." (PMID 38510083, 2024).
psychological distress (4 papers, 2020 to 2024). "This study found that PM decreased psychological distress by correcting markers like testosterone and also inhibiting NLRP3 inflammasome." (PMID 39479136, 2024). "A prospective clinical study reveals that pioglitazone metformin complex alleviates psychological distress via inhibiting NLRP3 inflammasome in patients with polycystic ovary syndrome comorbid psychological distress." (PMID 36408212, 2022). "This study is the first to reveal that PM alleviates psychological distress via inhibiting NLRP3 inflammasome and improves several markers, including total testosterone." (PMID 32410849, 2020). "The preliminary research of our team found that NLRP3 inflammasome was activated in patients with PCOS comorbid psychological distress compared with patients with PCOS." (PMID 32410849, 2020). "The authors concluded that PM alleviates psychological distress by inhibiting NLRP3." (PMID 37446154, 2023). "Thus, NLRP3 inflammasome and inflammation play important roles in psychological distress." (PMID 32410849, 2020). "However, the fact that PM reduces psychological distress and NLRP3 activity does not necessarily indicate a mechanistic relationship between these two effects." (PMID 37446154, 2023).
pulmonary edema (4 papers, 2022 to 2025). Accumulation of fluid in the lung tissues causing disturbance of the gas exchange that may lead to respiratory failure. "The increased NLRP3 expression observed in our study at 4 h after FE coincides with the onset of pulmonary edema, suggesting a causal relationship between NLRP3 activation and the pathogenesis of FE-induced ARDS." (PMID 40806699, 2025). "Fat embolism significantly increased pulmonary NLRP3 expression, lipid peroxidation, IL-1β release, and macrophage infiltration within four hours, accompanied by severe pulmonary edema." (PMID 40806699, 2025). "Compared with the FE-alone group, intravenous injection of MCC950 (10 mg/kg, I.V.)significantly reduced FE-induced pulmonary edema from 81.12% ± 1.34% to 78.13% ± 0.65%, indicating that NLRP3 mediates FE-induced pulmonary edema." (PMID 40806699, 2025). "Our findings demonstrate that FE leads to a significant upregulation of NLRP3 expression in the lungs, which correlates temporally with the development of pulmonary edema." (PMID 40806699, 2025). "Mechanical stretch induced the degradation of tight junction proteins such as occludin, potentially leading to pulmonary edema; however, the degradation of occludin was decreased in EX + MV group, in which NLRP3 was downregulated by aerobic exercise." (PMID 36456896, 2022). "We found that inhibition of the NLRP3 inflammasome by MCC950 could significantly inhibit pulmonary edema in HF mice." (PMID 35287557, 2022). "Moreover, activation of the NLRP3 inflammasome induces pyroptosis, emitting inflammatory cytokine that damage lung epithelial cells, disrupt alveolar structure, increase capillary permeability, and lead to pulmonary oedema and impaired gas exchange." (PMID 39623879, 2024). "However, NLRP3 knockout reduced the release of these inflammatory mediators, decreased inflammatory cell infiltration in lung tissues, improved alveolar‐capillary permeability, and reduced pulmonary oedema." (PMID 39623879, 2024). "Furthermore, administration of the NLRP3 antagonist, MCC950, effectively alleviated FE-induced pulmonary edema, lipid peroxidation, and histopathological lung damage through blockade of the ERK cascade." (PMID 40806699, 2025).
reflux esophagitis (4 papers, 2022 to 2025). "This study aims to further investigate the mechanism by which miR- 223 - 3p inhibits reflux esophagitis through targeting the NLRP3 inflammasome." (PMID 40360974, 2025). "The study found that miR- 223 - 3p was significantly downregulated in the reflux esophagitis model, while NLRP3 and its downstream inflammatory factors were significantly upregulated." (PMID 40360974, 2025). "This contradictory phenomenon requires further research to clarify the regulatory role of miR- 223 - 3p on the NLRP3 inflammasome in reflux esophagitis." (PMID 40360974, 2025). "Our study found that miR- 223 - 3p is significantly downregulated in the reflux esophagitis model, whereas NLRP3 and its downstream effectors, such as caspase- 1, IL- 1β, and IL- 18, are significantly upregulated." (PMID 40360974, 2025). "This study demonstrates that miR- 223 - 3p plays a key role in reducing inflammation and cellular damage in reflux esophagitis by targeting the NLRP3 inflammasome." (PMID 40360974, 2025). "Our study found that miR- 223 - 3p can significantly ameliorate the inflammatory response in reflux esophagitis by targeting the NLRP3 inflammasome, providing a new therapeutic approach for reflux esophagitis." (PMID 40360974, 2025). "A reflux esophagitis cell model was constructed to assess the expression levels of miR- 223 - 3p and NLRP3." (PMID 40360974, 2025). "Our results indicate a significant downregulation of miR- 223 - 3p in the reflux esophagitis model, while the expression of the NLRP3 inflammasome and its related inflammatory factors were significantly upregulated." (PMID 40360974, 2025). "This study delves into the mechanism by which miR- 223 - 3p inhibits reflux esophagitis through targeting the NLRP3 inflammasome, thereby enriching our understanding of the pathophysiology of reflux esophagitis." (PMID 40360974, 2025). "This study has validated the protective role of miR- 223 - 3p in reflux esophagitis through a series of experiments and revealed its mechanism of action in inhibiting the inflammatory response by targeting the NLRP3 inflammasome." (PMID 40360974, 2025). "Compared with the model group, overexpression of miR- 223 - 3p alone improved bile and acid-induced reflux esophagitis and reduced the expression levels of NLRP3 inflammasome activation-related proteins." (PMID 40360974, 2025). "Based on previous experimental results, we hypothesized that miR- 223 - 3p may influence the development of reflux esophagitis by regulating the activation of the NLRP3 inflammasome." (PMID 40360974, 2025). "The results revealed a significant decrease in miR- 223 - 3p expression during the development of reflux esophagitis in HET- 1 A cells (P < 0.001), accompanied by significant increases in the expression levels of caspase- 1, NLRP3, and GSDMD (P < 0.05)." (PMID 40360974, 2025). "In miR- 233 - 3p overexpression and knockdown cell lines with or without NLRP3 overexpression, we then investigate the function of miR- 223 - 3p-mediated NLRP3 inflammasome expression in reflux esophagitis." (PMID 40360974, 2025).
Retinal atrophy (4 papers, 2023 to 2026). A nonspecific term denoting wasting, especially as a result of degeneration, of the retinal pigment epithelium (RPE) and neurosensory retinal cells. "We next examined how retinal Chlamydia pneumoniae-related NLRP3 inflammasome activation components relate to retinal atrophy and a spectrum of cerebral AD pathological indices and clinical outcomes." (PMID 41571675, 2026). "Previous studies have reported retinal vasculitis, retinal atrophy, chorioretinitis, cystoid macular edema and epiretinal membrane in NLRP3-AID patients." (PMID 37480029, 2023).
rosacea (4 papers, 2017 to 2024). A chronic erythematous skin disorder that affects the face. "Recently, the use of a NLRP3-specific inhibitor reduced LL-37-triggered rosacea symptoms, demonstrating the role of NLRP3 in rosacea pathogenesis." (PMID 38450615, 2024). "IL1B, IL6, NLRP3, and TNFa were important characteristic factors and critical mediators in the inflammation of rosacea." (PMID 38250077, 2023). "The pro-inflammatory cytokines including IL1B, NLRP3, and TNFa were also significantly upregulated in rosacea-like skin lesions of WT mice and remarkably downregulated in those of OPN KO mice." (PMID 38250077, 2023). "Interestingly, the rosacea patients who expressed higher OPN also expressed higher IL6, IL1B, NLRP3, and TNFa, suggesting that there was a correlation between the expression of OPN and pro-inflammatory factors in rosacea." (PMID 38250077, 2023).